CD4 (CD4 molecule)
Diseases named in the same sentence as CD4 in open-access papers (continued):
Sharing a sentence is not in itself a finding about the gene and the disease.
pertussis (46 papers, 2010 to 2025). A contagious bacterial respiratory infection caused by Bordetella pertussis. "CD4+ T cells secreting both IL-9 and IL-17 have been shown to be associated with pertussis-specific responses after the vaccination." (PMID 34200795, 2021). "Loss of multi-epitope specificity in memory pertussis CD4+ T cell responses could play a role in waning effectiveness of pertussis immunity in older age groups." (PMID 24391789, 2013). "Future studies will compare the patterns of CD4+ T cell polarisation in response to pertussis vaccine antigens in a subcohort of infants enrolled in stage one." (PMID 38857311, 2024). "Our recent paper showed that mucosal delivery of BcfA-adjuvanted acellular pertussis vaccines elicited CD4+IL-17+ tissue-resident memory T cells (TRM) in the nose and reduced nasal bacterial burden." (PMID 39267766, 2024). "Experimental pertussis vaccines, when delivered i.n., generate CD4+ TRM cells in mice which prevent nasal colonization." (PMID 37275891, 2023). "The availability of standardized robust assays for the quantification of cytokine-producing CD4+ T cells specific for Bp antigens, as described here, is essential for the evaluation of immunological responses to pertussis vaccines." (PMID 36814927, 2023). "While serum antibodies are the most currently used biomarker for new vaccine evaluation, the role of CD4+ T lymphocytes in protection against pertussis is now largely accepted." (PMID 36814927, 2023). "Regarding cellular immunity, 15 days after vaccination, frequency of pertussis-specific CD4+ T cells, quantified by staining for IFN-γ, IL-2 and TNF-α, was equivalent in both groups supporting the induction of T cell immunity." (PMID 37468500, 2023). "It is seen that whole-cell pertussis vaccines induce CD4 T memory cells that are resident in the lungs and are more effective at inducing long-term immunological memory against pertussis." (PMID 36298443, 2022). "Example human studies include the characterisation of transcriptomic profiles of pertussis-specific CD4+ T-cells from aP- versus wP-primed donors, in order to shed light on the nature of the key differences between the infant vaccines." (PMID 34452002, 2021). "Declined CD4+ T-cell responsiveness to Bp is suggested to contribute to the burden of pertussis in older adults." (PMID 35822011, 2021). "As a possible intervention to enforce pertussis specific immunity, it was recently shown that older adults do mount both antibody and CD4+ T-cell booster responses to an acellular pertussis booster dose." (PMID 35822011, 2021). "For a more effective control of pertussis, also in the growing elderly population, induction and maintenance of protective CD4+ T-cell responses to Bp should be better understood." (PMID 35822011, 2021). "The control of pertussis requires the development of next generation vaccines that induce durable protective immunity, including Th1/Th17 lineage memory CD4+ T-cells." (PMID 32429152, 2020). "Here, we applied a novel whole blood assay to determine Th lineage differentiation of B. pertussis specific CD4+ T-cells in small volumes of whole blood in a clinical pertussis booster study in various age cohorts." (PMID 32429152, 2020). "We show, for the first time in the context of pertussis, that using a whole blood assay it is possible to detect Bp specific CD4+ T-cells of all functional Th lineages at low frequencies." (PMID 32429152, 2020). "Treatment of mice with AZM during immunization with a whole cell pertussis (wP) vaccine also inhibited the induction of tissue-resident CD4 T cells and IL-17-production in the lungs and CD49d+ CD4 T cells in the spleen after B. pertussis challenge." (PMID 30105030, 2018). "Others also described that wP-primed adolescents showed less terminally differentiated pertussis-specific CD4+ T-cell responses than aP-primed adolescents." (PMID 29416544, 2018).
pertussis (continued). "Knowledge on the breadth and quality of pertussis-specific CD4+ T cell responses at the epitope level is important yet lacking." (PMID 24391789, 2013). "Compared to the pertussis-specific memory CD4+ T cells in infants, relatively more cells in adults were shown to have an end-stage CCR7−CD27− differentiation memory phenotype." (PMID 24391789, 2013). "While the gene expression profile of atopy-specific CD4+ T cells are completely Th2, the gene expression profile of pertussis-specific CD4+ T cells is besides Th2 also Th1." (PMID 24391789, 2013). "Altogether, these results indicate that significant pertussis-specific CD4+ T responses can still be detected years after pertussis infection." (PMID 24391789, 2013). "In contrast, the breadth of the pertussis-directed CD4+ T cell response seemed dependent on age and closeness to infection." (PMID 24391789, 2013). "In this study we interrogate quantitative and qualitative aspects of pertussis epitope specific CD4+ T cell responses in B. pertussis exposed individuals, to identify eventual biomarkers of waning immunity." (PMID 24391789, 2013). "The breadth of the pertussis-specific CD4+ T cell response seems dependent on age and time after infection." (PMID 24391789, 2013). "In summary, our study provides more insight in the quality and maintenance of pertussis-specific CD4+ T cells in (ex-)pertussis patients." (PMID 24391789, 2013). "Our results additionally showed higher numbers of pertussis-specific CD3+CD4+ effector memory T-cells in 9 years old children compared with 4 years old children." (PMID 22860033, 2012). "Four weeks after the adolescent aP vaccination CD8+CD69+ activated T cells were augmented when PBMC were stimulated with all four tested pertussis antigens, whereas CD4+CD69+ T cells were decreased in FHA, PRN and FIM stimulated cultures." (PMID 21408149, 2011). "Natural infection with B. pertussis and immunization with wP vaccines prevent pertussis disease and infection of the respiratory tract, and this is associated with the recruitment of IL‐17+ and IFN‐γ+ CD4+ tissue‐resident memory T (TRM) cells to respiratory tissues in mice and humans." (PMID 40629997, 2025). "Additionally, CD25 on transitional B cells and CD3 on CD28+ CD4+ T cells play important roles in protecting against pertussis." (PMID 39612418, 2024). "Thus, this assay appears as a promising test for evaluation of Bp antigen-specific CD4+ T cells induced by current and next generation pertussis vaccines." (PMID 36814927, 2023). "Previous studies suggest that pertussis vaccine antigens can induce CD4+ and CD8+ T-cells responses which may result in a slower loss of antibodies and confer longer-term immunity." (PMID 34294074, 2021). "Whole blood samples, collected longitudinally from 73 participants representing four age cohorts in a clinical study, were used to evaluate Bp specific CD4+ T-cell responses around an acellular pertussis booster vaccination with a registered combination vaccine." (PMID 32429152, 2020). "However, several murine studies have demonstrated an important role for CD4+ Th1/Th17 cells in long-lasting protection, and these are often considered as critical effectors for novel pertussis vaccines." (PMID 31333656, 2019). "We used the murine model to evaluate whether the OMVs-based candidate pertussis vaccine induced systemic antigen-specific immune responses and CD4 T cells with a TRM cell phenotype in lungs." (PMID 31106160, 2019). "Steering towards an anti-bacterial Th1 profile and improving the breadth and long-term proliferative capacity of pertussis CD4+ T cell responses may elongate immunity against pertussis." (PMID 24391789, 2013). "Recent genomic studies indicate that, although on a superficial level similar Th2 responses are observed, the gene expression network is different for pertussis-specific CD4+ T cells (induced by acellular pertussis vaccination) compared to e.g. allergen-specific CD4+ T cells." (PMID 24391789, 2013).
pertussis (continued). "Long-lived Th1 CD4+ T cells are essential for protective immunity against pertussis." (PMID 24391789, 2013). "However the fact that within a single epitope-specificity distinct Th cytokine profiles are found, suggests some degree of flexibility in the pertussis-specific CD4+ T cell offspring." (PMID 24391789, 2013). "In addition to antibodies, pertussis-specific Th1 and Th17 type CD4+ T cells are essential for protective immunity against B. pertussis challenge in mice." (PMID 24391789, 2013). "Next to pertussis-specific CD8+ memory T cells that may contribute to protection against clinical pertussis, we believe that also CD4+ T cells producing Th1-cytokines may play an important role in protection of children against clinical pertussis." (PMID 22860033, 2012). "Pertussis immunization leads to specific antibody production with the help of CD4+ T cells." (PMID 21408149, 2011). "Also, inherent to the study design, in adults Bp-specific CD4+ memory T cells primed through childhood vaccination experienced a substantially longer maintenance period preceding the clinical pertussis event, studied in this work, compared to their counterparts in the younger group." (PMID 35822011, 2021). "Therefore we selected four Prn- and three Ptx- CD4+ T cell epitopes and compared direct ex vivo lymphoproliferative capacity, quality and breadth of epitope-specific CD4+ T cell responses, cross-sectionally in various groups of (ex-)pertussis patients and household contacts." (PMID 24391789, 2013). "The selected peptide panel appeared a useful tool to characterize Prn- and Ptx-specific CD4+ T cell responses at the single specificity level, since all selected Prn- and Ptx-peptides were immunogenic and subtle differences in the breadth of the pertussis specific response were identified." (PMID 24391789, 2013). "Nasal administration of aPV/BcfA can generate Th17+CD4+ TRM cells, effectively preventing the transmission and recurrence of pertussis." (PMID 39802636, 2025). "This study provides the first evidence that CD4 TRM cells are recruited and persist in the human respiratory tissues for 20–30 years after primary immunization with pertussis vaccines." (PMID 38290045, 2024). "Our study results indicate that 11 types of immune cells have a protective effect against pertussis, with the strongest protection observed from CD25 on CD28+ CD4+ cells (OR = 0.3533, CI = 0.1636–0.7627, P = .008)." (PMID 39612418, 2024). "Parenteral injection of pertussis OMV vaccines has been shown to produce mixed Th1/Th2/Th17 and CD4+ TRM cell responses." (PMID 37242993, 2023). "CD4 TRM cells that release IFN-γ and IL-17, which are known to increase the adaptive immunity against pertussis, are also present in the lungs of mice injected with the OMV vaccine." (PMID 36298443, 2022). "Despite comparable pertussis-specific T-cell proliferation between the two infant groups, HIV exposure significantly diminished measurable CD4+ and CD8+cytokine polyfunctionality in response to Bp stimulation." (PMID 34452002, 2021). "We earlier documented reduced in Bp-specific proliferative responsiveness in ex-pertussis cases, using a 3H thymidine assay and whole PT or single PT and PRN CD4+ T-cell epitopes as antigenic stimulation, starting at the age of 30 years." (PMID 35822011, 2021). "Besides adding to the insight in the presence, quality and maintenance of single epitope-specific CD4+ T cells in (ex-)pertussis patients in general, our peptide panel may provide information on the breadth of the Prn- and Ptx-specific response at the single donor level." (PMID 24391789, 2013). "The role of this dual IFN-γ secretion by CD4+ and CD8+ T lymphocytes in pertussis remains to be investigated." (PMID 22550536, 2012).
pertussis (continued). "Our findings demonstrate that immunization with licensed pertussis vaccines induces antigen‐specific CD8+ Treg cells that secrete IL‐10, which, together with CD4+ Treg cells, suppress activation of IL‐17‐secreting T cells, known to play a crucial role in protective adaptive immunity to B. pertussis." (PMID 40629997, 2025). "In our study population, who had not been recently boosted with pertussis vaccines, B. pertussis-specific CD4 T-cell responses were weak or undetectable in blood." (PMID 38290045, 2024). "Additionally, these B. pertussis-specific splenic Th1 and Th17 memory responses, as well as CD4+ TRM cells producing IL-17 and IFN-γ in the lungs induced by pertussis-OMV, play an important role in maintaining immune persistence." (PMID 37242993, 2023). "The characterization of B. pertussis (Bp) antigen-specific CD4+ T cell cytokine responses should be included in the evaluation of immunogenicity of pertussis vaccines but is often hindered by the lack of standardized robust assays." (PMID 36814927, 2023). "However, the numbers of activated T cells (CD4+, CD8+ and γδ T cells) were much higher in the samples from the DTaP-primed group incubated with the pool of pertussis antigens than in those from the DTaP-primed or TBS groups incubated with medium." (PMID 33815369, 2021). "It is indeed intriguing that despite lower frequency of CD4 and higher CD8 cells in the PT infants and lower number of antigen-presenting cells such as dendritic cells and monocytes in the PT1 infants, anti-pertussis antibody titers were comparable with the FT infants." (PMID 33968011, 2021). "Notably, in both groups of children, CD3+CD4+ effector memory cells producing simultaneously IFN-γ and TNF-α upon stimulation with pertussis antigens were found, indicating that one cell is able to produce more than 1 cytokine." (PMID 22860033, 2012). "Thus it seems that also for whole cell pertussis vaccine, TLR2 or TLR4 activation has little influence on CD4+ T cell proliferation." (PMID 21203418, 2010). "In addition, and in contrast to acellular pertussis vaccines, BPZE1 also cross-protected against Bordetella parapertussis infection, but in this case only the transfer of CD4+ T cells conferred protection." (PMID 20419113, 2010). "While the reported IgE responses are not conclusive, further studies of CD4+ T cell polarisation in response to pertussis antigens, along with primary outcome data will provide a comprehensive picture of the atopic immunophenotypic responses across the study groups." (PMID 38857311, 2024). "The cell clusters derived from CD4+ or CD8+ T cells were not predictive of IgG pertussis vaccine response at weeks 15 and 36, for CD4 clusters at birth: AUC = 0.73, p = 0.064; for CD8 clusters: AUC = 0.69, p = 0.12; at week 4: CD4 clusters AUC = 0.70, p = 0.055; CD8 clusters AUC = 0.70, p = 0.053." (PMID 38744812, 2024). "Thus, these pertussis epitope-specific CD4+ T cell responses are not fixed to one Th cytokine profile." (PMID 24391789, 2013). "However, perhaps more likely, aging of the CD4+ T cell compartment could play a role in the lack of multi-epitope specificity in older ex-pertussis patients." (PMID 24391789, 2013). "Proliferation of central memory compartment of CD4 and CD8 T cells with polyfunctional response in FT infants with or without anti-pertussis antibodies revealed that these infants are likely to be protected following exposure to the pathogen." (PMID 33968011, 2021). "Consistent with natural infection, effective pertussis immunisation in mice has been shown to depend on induction of CMI, with no protection established in mice lacking all T-cells or CD4+ T-cells." (PMID 34452002, 2021). "Vehicle- and guanabenz-treated recipient mice both had significantly higher numbers of live CD4+ T cells within the CNS on PCT3 and PCT6 compared with non-recipient mice injected with pertussis only, indicating that the drug does not prevent initial T cell infiltration into the CNS." (PMID 25766071, 2015).
squamous cell carcinoma (46 papers, 2011 to 2025). A carcinoma arising from squamous epithelial cells. "For squamous cell carcinoma patients, a higher percentage of regulatory T cells and naïve CD4+ T cells was associated with a marginally poorer overall OS." (PMID 36793597, 2023). "This shows that higher B‐cell and naïve CD4 T‐cell fractions were associated with better OS in adenocarcinoma, while higher fractions in squamous cell carcinoma are associated with worse OS." (PMID 32547744, 2020). "For squamous cell carcinoma, regulatory T cells and naïve CD4 T cells were associated with shorter survival, and both were lower compared to adenocarcinoma patients." (PMID 32547744, 2020). "Stratified analysesrevealed that the survival of patients with squamous cell carcinoma has a positive association with high density of CD4+ or CD8+ TILs alone." (PMID 26871598, 2016). "Adenocarcinoma patients with survival data (n = 587) showed higher fractions of resting mast and resting CD4 T cells, and lower M0 macrophages than squamous cell carcinoma (n = 254), which were associated with OS (HR = 0.95, P = 0.04; HR = 0.97, P = 0.01; HR = 1.03, P = 0.01, respectively)." (PMID 32547744, 2020). "Adenocarcinoma, as compared with squamous cell carcinoma, showed increased resting CD4 T cells and resting mast cells, both associated with longer survival, while having lower proportions of M2 macrophages and follicular helper T cells, associated with worse survival." (PMID 32547744, 2020). "For squamous cell carcinoma patients (n = 254), resting mast cells were associated with a better OS (HR = 0.94, P = 0.01), while a higher percentage of regulatory T cells and naïve CD4 T cells were associated with a marginally poorer overall OS (HR = 1.12, P = 0.06; HR = −1.1, P = 0.06)." (PMID 32547744, 2020). "CD4+ cells were more prevalent in patients with well-differentiated tumors (G1 and G2) and lower levels of CD4+ infiltration were found in squamous cell carcinoma (SCC) compared to other histological subtypes." (PMID 41007768, 2025). "While this environment differs for basal and squamous cell carcinoma, the cellular players within both create an immunosuppressed environment by downregulating effector CD4+ and CD8+ T cells and promoting the release of pro-oncogenic Th2 cytokines." (PMID 37173918, 2023). "Using a microfluidic chip, we injected HSC-3 cells (an oral tongue squamous cell carcinoma cell line) embedded in a human tumor-derived matrix “myogel/fibrin” together with NK, CD4+, and CD8+ T cells in separate channels." (PMID 35359980, 2022). "The YTHDF1 mRNA expression was also significantly negatively associated with CD4, CD8, and FOXP3 mRNA expression in squamous cell carcinoma." (PMID 36479088, 2022). "Compared to squamous cell carcinoma, adenocarcinoma had higher fractions of memory B cells, resting mast cells and CD4 T cells." (PMID 32547744, 2020). "This phenomenon was observed after STAT1 expression in a human squamous carcinoma cell line and type I interferon treatment of murine L-929 cells, human Daudi lymphoblastoid cells and isolated CD4+ lymphocytes from MS patients." (PMID 31817188, 2019). "Among CD3+ T cells, CD4+ T cells were the most frequent (28.6% in adenocarcinoma and 22.1% in squamous cell carcinoma) followed by CD8+ T cells (23.9% in adenocarcinoma and 18.2% in squamous cell carcinoma)." (PMID 30774636, 2018). "Intraepithelial tumor infiltrating lymphocytes: CD8+, CD4+, FOXP3+, CD56+, tumor associated macrophages: CD68+, and GZB+ cells were calculated in 85 vulvar squamous cell carcinomas with previously defined p16Ink4a and high-risk HPV-status." (PMID 28515351, 2017). "There was a higher T lymphocyte count in the stroma in adenocarcinomas than in squamous cell carcinomas (p < 0.03), attributable to differences in the CD4+ T subset (p < 0.02)." (PMID 27689405, 2016). "CD4+ T cells were found more abundantly in the stroma of squamous cell carcinoma compared with adenocarcinoma (P < 0.05)." (PMID 26604855, 2015).